NLRP3 (NLR family pyrin domain containing 3)
Diseases named in the same sentence as NLRP3 in open-access papers (continued):
Sharing a sentence is not in itself a finding about the gene and the disease.
neurodegenerative disease (265 papers, 2012 to 2026). A disorder of the central nervous system characterized by gradual and progressive loss of neural tissue and neurologic function. "Conversely, the imbalance caused by deacetylase-regulated NLRP3 inflammasome underlies the chronic mild inflammation related to degenerative diseases." (PMID 39857301, 2025). "Conversely, the dysregulation of NLRP3 inflammasome acetylation underlies the chronic low-grade inflammation associated with degenerative diseases." (PMID 39857301, 2025). "A detailed understanding of the molecular networks governing ion homeostasis for NLRP3 inflammasome activation will lead to the development of therapeutic approaches for inflammatory and degenerative diseases associated with NLRP3 pathologies." (PMID 40307577, 2025). "The disruption of the regulation of NLRP3 inflammasome formation and activation has been implicated in neuroinflammation and the pathogenesis of some neurodegenerative diseases." (PMID 40649889, 2025). "Dysregulated activation of the NLRP3 inflammasome has been implicated in a range of diseases, including metabolic disorders and neurodegenerative diseases." (PMID 40806699, 2025). "There is increasing evidence that the cGAS-STING pathway is implicated in NLRP3-mediated neuroinflammation, contributing to neurodegenerative disease progression." (PMID 38481801, 2024). "The NLRP3 inflammasome, implicated in different neurodegenerative diseases encompassing TBI, has recently emerged as a possible target for ameliorating neuroinflammation and improving cognitive and motor function in TBI." (PMID 38708192, 2024). "Neurodegenerative diseases have been linked to several inflammasomes, with the pyrin domain-containing 3 (NLRP3) inflammasome being particularly important for the development and progression of these conditions." (PMID 39683782, 2024). "The NLRP3 inflammasome appears to be a major driver of neuroinflammation, neurodegenerative diseases and psychiatric disorders that have been linked to microglial hyperreactivity." (PMID 39392762, 2024). "Previously NLRP3/Caspase1/IL-1β has been implicated in central immune and neurodegenerative diseases." (PMID 37946206, 2023). "Neuroinflammation, specifically the NLRP3 inflammasome cascade, is a common underlying pathological feature of many neurodegenerative diseases." (PMID 36375694, 2023). "The ability to control its deactivation and/or identify the inhibitory pathways associated with NLRP3 opens therapeutic possibilities for slowing the progression of neurodegenerative diseases." (PMID 36771231, 2023). "The activation of the NLRP3 inflammasomes in microglial cells plays a vital role in the establishment of neurodegenerative diseases, including ALS, which cause the degeneration of surrounding motor neurons." (PMID 36231090, 2022). "Within the known inflammasomes, NLRP3 has been reported to be associated with neuroinflammation in the pathological onset of neurodegenerative diseases and secondary inflammation following TBI." (PMID 35893807, 2022). "In HD and other neurodegenerative diseases caused by aberrant aggregation of proteins including AD and PD, the NLRP3 inflammasome participates in disease progression." (PMID 35219323, 2022). "NOD-, LRR-, and pyrin domain-containing protein 3 (NLRP3) is the best characterized inflammasome and has been implicated in the development of neurodegenerative diseases." (PMID 34924922, 2021). "Dysregulation of the NLRP3 inflammasome has been associated with various neurodegenerative diseases." (PMID 34925047, 2021). "NLRP3 inflammasome activation has been implicated in the pathogenesis of neurodegenerative diseases, especially AD and PD." (PMID 33525754, 2021). "The NLRP3 inflammasome is also known to play a vital role in inflammation activation and has been implicated in various inflammatory diseases including neurodegenerative diseases." (PMID 33436909, 2021).
neurodegenerative disease (continued). "Despite the diverse range of mechanisms underlying these conditions, NLRP3 inflammasome activation and dysregulation are common features of several neurodegenerative diseases, both in the periphery and the CNS." (PMID 33776778, 2021). "Previous reports indicated that NLRP3 inflammasomes were associated with many neurodegenerative diseases, including PND." (PMID 34079457, 2021). "This review aims to summarise recent progress in our understanding of several neurodegenerative diseases, whose development and/or progression has been linked to inflammation involving activation of the NLRP3 inflammasome." (PMID 33776778, 2021). "Among the various types of inflammasomes, NLRP3 inflammasome is the well-known in neurodegenerative diseases, especially in AD and PD and the activation of the NLRP3 inflammasome causes the production of IL-1β and IL-18 in microglia cells." (PMID 34922574, 2021). "The NLRP3 inflammasome complex triggers caspase-1 activation, which is one of the causes of the pathogenesis of neurodegenerative diseases." (PMID 32751738, 2020). "NLRP3 is the most characterized and studied inflammasome receptor and NLRP3 alterations have been linked to several pathologies, including neurodegenerative diseases." (PMID 30941089, 2019). "Inflammasomes are linked to neurodegenerative diseases: activated NLRP3 was observed in Parkinson’s disease in the midbrain and cerebrospinal fluid." (PMID 30261895, 2018). "Interestingly, these two cytokines are both involved in the NLRP3 inflammasome pathway, which has been associated with other neurodegenerative diseases." (PMID 37268663, 2023). "The NLRP3 inflammasome coordinates inflammation in response to different pathogen- and damage-associated molecular patterns, being implicated in different infectious, chronic inflammatory, metabolic and degenerative diseases." (PMID 35199642, 2022). "However, emerging evidences indicate that the function of NLRP3 inflammasome is associated with many diseases including tumorigenesis, autoimmune disorders, and neurodegenerative diseases." (PMID 34502191, 2021). "Most importantly, inhibition of NLRP3 in animal models reduces the inflammatory response, decreases abnormal protein deposition, and corrects behavioral abnormalities associated with neurodegenerative diseases, suggesting the possibility of targeting NLRP3 inflammasome to treat such diseases." (PMID 32792920, 2020). "The NLRP3 inflammasome is a crucial signaling node in microglia that ultimately controls the maturation of pro-inflammatory interleukin (IL)-1β and IL-18 and has been linked to a multitude of neurodegenerative diseases." (PMID 31131421, 2019). "NLRP3 inflammasome activity is verified to be associated with neurodegenerative diseases." (PMID 31118933, 2019). "Preclinical studies have demonstrated that the inhibition of NLRP3 reduces behavioral outcomes and abnormal protein accumulation associated with neurodegenerative diseases, suggesting that targeting NLRP3 inflammasome could represent a novel therapeutic approach for neurodegenerative disorders." (PMID 35418995, 2022). "Therefore, our study suggests that fucoxanthin from Phaeodactylum tricornutum microalgae may be a potential singular therapeutic agent for inflammatory diseases as well as neurodegenerative diseases caused by NLRP3 inflammasome activation." (PMID 33436909, 2021). "Thus, our results provide reliable evidence that fucoxanthin may serve as a key candidate in the development of potential therapeutic agents for inflammatory diseases as well as neurodegenerative diseases caused by NF-κB and NLRP3 inflammasome activation." (PMID 33436909, 2021). "Moreover, NLRP3 and the molecules associated with its activation may be considered as biomarkers and predictive factors for other neurodegenerative diseases consequent to TBI." (PMID 32867310, 2020).
neurodegenerative disease (continued). "Background and Objectives: The NOD-like receptor family pyrin domain-containing 3 (NLRP3) inflammasome is a key innate immune complex, and its aberrant activation contributes to metabolic and neurodegenerative diseases." (PMID 41752782, 2026). "The robust NLRP3 inflammasome response, upregulation of NLRP3 and IL-1β following LPS + ATP/NG stimulation, highlights their relevance for studies of inflammasome-targeting drugs in neurodegenerative diseases." (PMID 41596340, 2026). "The NLRP3 inflammasome is a key driver in inflammatory, infectious, metabolic, and neurodegenerative diseases." (PMID 41998138, 2026). "Assembly of the NLRP3 inflammasome further promotes activation of caspase-1, IL-1β, and IL-18, which are key contributors to neurodegenerative pathology and further support the role of the TLR/ NFκB/NLRP3 axis in neurodegenerative disease." (PMID 40507859, 2025). "By targeting multiple pathways, such as NF-κB and the NLRP3 inflammasome, they exert anti-inflammatory and antioxidant effects, contributing to the prevention of cardiovascular and neurodegenerative diseases." (PMID 40508016, 2025). "More and more studies have shown that the cGAS/STING/NLRP3 signaling pathway plays an important role in Neurodegenerative diseases." (PMID 40463371, 2025). "Small interfering RNAs (siRNAs) targeting NLRP1, NLRP3, and caspase-1 have shown promise in models of neurodegenerative diseases." (PMID 41280719, 2025). "The NLRP3 inflammasome, which produces IL-1β and IL-18, is dysregulated in neurodegenerative diseases like Alzheimer’s and Parkinson’s." (PMID 40558545, 2025). "In experimental models, knockout of NLRP3 has been shown to reduce neuroinflammation and slow the progression of neurodegenerative diseases." (PMID 40066444, 2025). "NLRP3, a central driving factor in neurodegenerative diseases, primarily facilitates the pathological advancement of PD through the assembly and activation of inflammasomes in microglia, thereby mediating neuroinflammation." (PMID 40830103, 2025). "As pyroptosis is increasingly recognized for its connection to neurodegenerative diseases, this study provides insights into the molecular mechanisms of neuronal pyroptosis mediated by the NLRP3 inflammasome in the context of HERV-W env." (PMID 39859234, 2025). "In contrast, neurodegenerative diseases are predominantly characterized by NLRP3-mediated pyroptosis." (PMID 39994107, 2025). "In neurodegenerative diseases and CNS inflammation-related disorders, the NLRP3 inflammasome and its mediated activation of GSDMD play significant roles and have become a major focus of research." (PMID 40552323, 2025). "Dysregulated NLRP3 activation is involved in many inflammatory, metabolic, and neurodegenerative diseases." (PMID 40164768, 2025). "In neurodegenerative disease models, A20 has been shown to prevent microglial activation and NLRP3-driven inflammatory pathways, further reinforcing its potential relevance in the context of AD-associated immune responses." (PMID 41162989, 2025). "Neurological diseases can be broadly categorized into cerebrovascular diseases, and neurodegenerative diseases, which are closely associated with the AIM2-caspase-1-GSDMD and NLRP3-caspase-1-GSDMD inflammasome signaling pathways." (PMID 39994107, 2025). "Using a murine model of AD that accurately mimics multiple facets of human neurodegenerative diseases, we evaluated the therapeutic capacity of targeting the NLRP3 inflammasome using a novel and highly selective brain penetrant inhibitor." (PMID 40343261, 2025). "NLRP3 is a critical component of the NLRP3 inflammasome, which plays a crucial role in regulating inflammatory responses, particularly in neurodegenerative diseases where inflammation contributes to neuronal damage." (PMID 40003703, 2025).
neurodegenerative disease (continued). "The NLRP3 inflammasome is a multiprotein complex that plays an important role in several neurodegenerative diseases, being essential for cleavage and subsequent release of IL1b from activated microglia." (PMID 41562096, 2025). "Among various inflammasomes, Nucleotide-binding oligomerization domain leucine-rich repeat and pyrin domain-containing protein 3 (NLRP3) is the best-characterized inflammasome related to inflammatory and neurodegenerative diseases." (PMID 38421496, 2024). "The excessive or altered regulation of NLRP3 inflammasome activity is related to the pathogenesis of a wide variety of inflammatory, autoimmune, and degenerative diseases." (PMID 39201678, 2024). "Utilizing MCC950 has also been of interest to mitigate NLRP3-mediated inflammation related to neurodegenerative disease in animal models." (PMID 38702410, 2024). "NLRP3, one of the most common inflammasomes, plays an important role in mediating the neuroinflammation process of neurodegenerative diseases." (PMID 38630150, 2024). "Intense crosstalk between TLRs and the inflammasome pathway has been described in neurodegenerative diseases since the TLR activation acts as a priming signal for the expression of NLRP3, pro-IL-18, and pro-IL-1β." (PMID 38791415, 2024). "In summary, elevated NLRP3 expression in microglia and brain endothelial cells contributes to the pathogenesis of brain injury and neurodegenerative diseases like VaD." (PMID 39764140, 2024). "In neurodegenerative diseases, inflammasome activation, particularly the NLRP3 inflammasome activation, has been extensively studied for its role in AD and PD, but its specific pathogenic mechanisms in HD and ALS are not well understood." (PMID 39710713, 2024). "As a key inflammatory factor, the nucleotide-binding oligomerization domain (NOD)-like receptor protein 3 (NLRP3) inflammasome plays a crucial role in neuroinflammation and the progression of neurodegenerative diseases." (PMID 39764140, 2024). "Overall, these findings emphasize NLRP3’s central involvement in age-related astrogliosis and the progression of neurodegenerative diseases." (PMID 39301197, 2024). "The overactivation of the NLRP3 inflammasome impairs microglial autophagy, exacerbating neurodegenerative disease mechanisms, thus supporting the application of microglial autophagy inducers and NLRP3 inhibitors." (PMID 39337436, 2024). "Previous studies demonstrated that Nod-like receptor protein 3 (NLRP3) inflammasome participates in various inflammatory and neurodegenerative diseases." (PMID 38145993, 2024). "NLRP3 inflammasome plays a critical role in the pathogenesis of various diseases, including cardiovascular diseases, metabolic disorders, and neurodegenerative diseases." (PMID 39834371, 2024). "NLRP3 is the most widely studied inflammasome complex among the known inflammasome types, and its role in several different neurodegenerative diseases has been investigated." (PMID 38920626, 2024). "OLT1177, TRANILAST, ORIDONIN, JC171 and MNS all inhibit NLRP3 inflammasome activation yet via different mechanisms, and are applicable to only a few neurodegenerative diseases." (PMID 39710713, 2024). "Extensive reviews and studies highlight NLRP3’s crucial role in developing neurodegenerative diseases." (PMID 39301197, 2024). "Given the NLRP3 inflammasome’s critical role in microglial activation and numerous neurodegenerative diseases, we utilized IF staining and western blotting to gauge its activation." (PMID 37968531, 2024). "Emerging evidence suggests that the inhibition of autophagy exacerbates the extent of NLRP3 inflammasome-mediated inflammation and neurodegenerative diseases." (PMID 39411285, 2024). "Of these, miR-223-3p has been shown to regulate the NLRP3 inflammasome in several neurodegenerative diseases." (PMID 38920626, 2024).
neurodegenerative disease (continued). "We demonstrate that NOX4 is a key player in NLRP3 inflammasome activation suggesting NOX4 pharmacological inhibition as a potent therapeutic approach in neurodegenerative diseases." (PMID 37760032, 2023). "Since NLRP3 inhibitors are currently in clinical development for neurodegenerative diseases, including PD, these findings also support a potential therapeutic avenue for treatment of SARS-CoV-2 driven neurological manifestations." (PMID 36316366, 2023). "Excessive activation of NLRP3 inflammatory bodies impairs microglial autophagy and worsens neurodegenerative diseases." (PMID 37110714, 2023). "NLRP1, NLRP2, AIM2, NLRC4 and NLRP3 have been suggested to be involved in the progression of neurodegenerative diseases." (PMID 37433768, 2023). "In summary, ROS-mediated mitochondrial dysfunction combined with NLRP3 inflammasome activation contribute to progression of neurodegenerative diseases, including SNHL." (PMID 36891515, 2023). "Numerous neurodegenerative diseases share commonalties in their pathogenesis through activation of the NLRP3 inflammasome." (PMID 36740674, 2023). "In particular, NF‐κB activation leads to the transcription and functionalization of the NLRP3 inflammasome, which participates in NLRP3/caspase‐1 signaling in the pathological process of neurodegenerative diseases." (PMID 36987783, 2023). "Aberrant activation of the NLRP3 inflammasome in monocytes/microglia has been previously reported in different neurodegenerative diseases." (PMID 38004455, 2023). "In neurodegenerative diseases, amyloid proteins trigger NLRP3 inflammasome, leading to activation of CASP1 and release of IL-1β." (PMID 37578928, 2023). "Recent studies have implicated that NLRP3 inflammasome and the ASC specks play important roles in the propagation and spreading of neuroinflammation and misfolded protein aggregation in neurodegenerative diseases." (PMID 36740674, 2023). "Pilot studies using inhibitors of NLRP3 in mouse models of neurodegenerative diseases have proved this approach effective." (PMID 37268663, 2023). "As a result, inhibiting NLRP3 inflammation by modulating autophagy has been considered a targeted therapy for neurodegenerative diseases." (PMID 37110714, 2023). "Among several inflammasome types, the NLRP3 inflammasome is a well-characterized protein complex in neurodegenerative diseases, especially in AD." (PMID 37108458, 2023). "In neurodegenerative diseases, the mitochondria in microglia can be damaged by the misfolded protein aggregations and released mtDNA and ROS, which over-activates the NLRP3 inflammasome." (PMID 36704504, 2022). "In recent years, researchers have focused on the role of the NLRP3 inflammasome in several brain disorders, including neurodegenerative diseases, such as Alzheimer’s disease or Parkinson’s disease, TBI, and CNS infections." (PMID 35893807, 2022). "The NLRP3 inflammasome plays an important role in inflammatory reactions and is involved in the pathogenesis of several neurodegenerative diseases such as AD and PD." (PMID 35219323, 2022). "Nrf2 is a common therapeutic target in neurodegenerative diseases and can reduce NLRP3 overactivation, thereby reducing NLRP3-mediated neuroinflammation." (PMID 36232521, 2022). "It has been reported that the expression of NLRP3 in the brain of elderly rats is significantly higher than that of young rats, and the activation of NLRP3 is significantly increased in neurodegenerative diseases." (PMID 35401924, 2022). "Deficiency or inhibition of autophagy can exacerbate the pathology of NLRP3 inflammasome-mediated neurodegenerative diseases." (PMID 35250595, 2022). "The NLRP3 inflammasome plays a central role in many acute and chronic inflammatory and degenerative diseases, but the mechanisms that control its activation are poorly understood." (PMID 35401582, 2022). "Many studies have pointed that NLRP3-mediated inflammation played a vital role in degenerative diseases." (PMID 36466156, 2022).